LGALS3 (galectin 3)
Diseases named in the same sentence as LGALS3 in open-access papers (continued):
Sharing a sentence is not in itself a finding about the gene and the disease.
neurodegenerative disease (continued). "Of the many PAMPs and DAMPS that can activate TLR4, some have particular relevance to neurodegenerative disease such as amyloid-β (Aβ), α-synuclein and galectin-3 (described in further detail below)." (PMID 32709045, 2020). "This may reflect the pleiotropic role of galectin-3, which is upregulated not only in cardiac fibrosis but also in systemic processes such as aging, malignancy and neurodegenerative disease." (PMID 41158187, 2025). "Galectin-3 (GAL3) is known to have a detrimental function in neurodegenerative diseases." (PMID 37202527, 2023). "One of the most upregulated markers in neurodegenerative diseases is galectin-3 (GAL3)." (PMID 37202527, 2023). "This means that inhibition of galectin-3 may become a new strategy for the treatment of neurodegenerative diseases." (PMID 33414713, 2020). "Therefore, it has been suggested that galectin-3 may be an indicator of prognosis, mortality, or remission in neurodegenerative diseases." (PMID 36008956, 2022). "Galectin-3 may also play a role in inflammation amplifiers in neurodegenerative diseases." (PMID 34720894, 2021). "In the subgroup analysis by type of neurodegenerative diseases and galectin, it was shown that patients with AD, PD, and ALS have higher levels of galectin-3 expression, and in the case of patients with MS, higher expression of gal 9 was found." (PMID 36008956, 2022). "Further studies are necessary to understand the contribution of GPNMB and galectin-3 to FTD and related neurodegenerative disease." (PMID 33028409, 2020). "Collectively, these findings suggest that microglial galectin-3 plays a protective role in ALS, which appears different from most of the neurodegenerative diseases where the role of galectin-3 has been investigated so far; further investigation is required." (PMID 29867350, 2018).
inflammation (24 papers, 2013 to 2026). Aberrant reaction of the microcirculation characterized by movement of fluid and leukocytes from the blood into extravascular tissues. "Because LPS stimulation is implicated in promoting inflammatory cell infiltration in the liver and has been used to model acute and chronic liver inflammation in mouse models, we next quantified the Mac2 (encoded by Lgals3)-positive macrophages in liver sections by immunohistochemistry." (PMID 38097183, 2023). "The increase in galectin-3 in the circulation is due to cardiac inflammation, which stimulates the leakage of galectin-3 from various cells into the circulation." (PMID 37513890, 2023). "Our findings highlight cardiac inflammation and enhanced β-adrenoceptor activation in mediating elevated galectin-3 levels via cardiac release in the mechanism." (PMID 29844319, 2018). "Simvastatin attenuates LPS-induced oxidative acute lung inflammation, oxidative stress, and suppresses LPS-induced Galectin-3 expression in the lung tissue." (PMID 29853535, 2018). "Moreover, galectin-3 is required for microglia-mediated brain inflammation, while the suppression of galectin-3 ameliorates microglia-mediated pathogenesis by decreasing NFκB activation." (PMID 34122007, 2021). "Interestingly in DBRI, the galectin-3 levels were increased with a higher degree of statistical significance than for alpha-1-antitrypsin, which is a well-known indicator of lung inflammation." (PMID 25033447, 2014). "Since galectin-3 is readily expressed on the cell surface, and is readily secreted by injured and inflammatory cells, it has been suggested that cardiac galectin-3 could be a marker for cardiac disorders such as cardiac inflammation and fibrosis, depending on the specific pathogenesis." (PMID 32899694, 2020).
bacterial infection (20 papers, 2014 to 2025). "Galectin-3 plays a versatile role in bacterial infections by recognizing specific glycans on microbial surfaces." (PMID 40806347, 2025). "Previously, it was shown that galectin-3 is able to trap and aggregate bacteria, which is an important host protective mechanism of bacterial infection and colonization." (PMID 37000885, 2023). "A protective role of extracellular galectin-3 against S. pneumoniae infection was proved in a bacterial infection model." (PMID 35845133, 2022). "Galectin-3 reduced the combined efficiency of virus and bacterial infections, such as HSV-1 and P. aeruginosa." (PMID 35845133, 2022). "Previous reports have observed galectin-3 and -8 colocalized with Mtb, and galectin-3 in particular is often used as a go-to marker of membrane damage during bacterial infection (18, 33, –, 38)." (PMID 34225486, 2021). "Galectin-3, -8, and -9 have been reported to be recruited to damaged bacterium-containing vacuoles and to participate in the defense against bacterial infection." (PMID 33425778, 2020). "The highest level of galectin-1, galectin-3, and E-selectin was detected in the bacterial infection group." (PMID 27240351, 2016). "Furthermore, intranasal infection with S. suis induced an increase in galectin-3 expression, indicating a potential role for galectin-3 in the response to bacterial infections." (PMID 40696454, 2025). "However, the importance of galectin-3 in nasal mucus and its function in combating bacterial infections remain inadequately explored." (PMID 40696454, 2025). "We further demonstrate that meprin α/β heterodimers differentially process galectin-3 upon bacterial infection, in germ-free, conventionally housed (specific pathogen–free), or wildling mice, which in turn regulates the bacterial agglutination properties of galectin-3." (PMID 37000885, 2023). "Examples of PAMP Galectin-3 pathways are bacterial infections in which Galectin-3 recognizes the glycoconjugates of different bacteria, such as Helicobacter pylori, Neisseria meningitidis, Neisseria gonorrhoeae, Streptococcus pneumoniae, Klebsiella pneumonia, and Escherichia coli." (PMID 32455781, 2020). "Thus, there is at least indirect evidence that galectin-3 may limit bacterial infections in vivo, potentially by acting as an opsonin, but this requires further investigation." (PMID 31781126, 2019). "Regarding Th17 immunity against bacterial infection, Lgals3−/− mice exhibited normal clearance of C. rodentium, indicated by no obvious differences between WT and Lgals3−/− mice in body weight, bacterial load, colon length, and colonic CD4+ T cells, including CD4+IL17A+ cells and Tregs." (PMID 39504243, 2024).
metabolic disorders (18 papers, 2015 to 2026). "We thoroughly characterized the association patterns of galectin-1 and galectin-3 to established and exploratory markers of metabolic disease in a community-based cohort." (PMID 38777863, 2024). "Like leptin, galectin 3 is strictly associated with the development of metabolic disorders." (PMID 32859099, 2020). "Galectin-3 levels and secretion have been significantly elevated in metabolic diseases as compared to healthy subjects." (PMID 41590667, 2026). "Experimental studies indicate a role for galectin-1 and galectin-3 in metabolic disease, but clinical evidence from larger populations is limited." (PMID 38777863, 2024). "Plasma galectin-3 is also higher during early pregnancy in women with gestational diabetes, suggesting a role in metabolic disease." (PMID 38777863, 2024). "Circulating levels of chemerin, leptin, and galectin-3 are commonly elevated, while serum adiponectin levels are reduced in the obese and all of those changes are related to metabolic diseases." (PMID 37238973, 2023). "Taken together, these data suggest that galectin-3 is a surrogate marker, rather than a mediator of metabolic disorders, in which it might play a protective role, as part of an adaptive response." (PMID 26770660, 2016).
adenocarcinoma (14 papers, 2010 to 2026). A common cancer characterized by the presence of malignant glandular cells. "Recently, we have linked the expression of galectin-3 on the A549 epithelial cell line –an adenocarcinoma, to the activation of human basophils for the release of histamine and secretion of IL-4 and IL-13." (PMID 33154744, 2020). "When the ligand-target links between adenocarcinoma and macrophages were investigated, we identified CALM1, RPS19, GSTP1, and LGALS3 as prioritized adenocarcinoma expressed ligands." (PMID 35954218, 2022). "It is possible that response rates to galectin-3 inhibitors may differ depending on patients’ galectin-3 levels, with our data suggesting that adenocarcinoma may be the most likely to respond." (PMID 38539500, 2024). "We didn't reveal differences in cyclin D1 and galectin-3 expression in SCC and adenocarcinoma patients." (PMID 22024187, 2011). "We compared galectin-3 expression in two main histopathogical types: SCC and adenocarcinoma, but any statistical significant differences were revealed (Chi2 Yatesa 0.74, p = 0.390)." (PMID 22024187, 2011). "We analyzed the prognostic value of galectin-3 expression in all patients with NSCLC and separately in patients with SCC and adenocarcinoma, and separately in every stage, but we didn't find any statistical significant differences." (PMID 22024187, 2011). "Moreover we analyzed the prognostic value of cyclin D1 expression and galectin-3 in all examinated patients and separately in SCC and in adenocarcinoma and in all stages, but we didn't find any statistical differences." (PMID 22024187, 2011).
kidney (11 papers, 2010 to 2024). "Long term upregulation of both IBA-1-ir and galectin-3/Mac-2-ir microglia has also been observed in the subventricular zone (SVZ) following middle cerebral artery occlusion." (PMID 20507613, 2010).
neurological diseases (10 papers, 2019 to 2025). "Brief summary of clinical studies on the level and impact of Galectin-3 on main clinical findings in various neurological disorders." (PMID 35875353, 2022). "Recent studies in mouse models have demonstrated that Galectin-3 is involved in multiple inflammatory processes in diverse neurological diseases and that it promotes Aβ toxicity and oligomerization in AD." (PMID 36076283, 2022). "Galectin-3 has recently been confirmed to be involved in the processes of a variety of neurological disorders." (PMID 34900086, 2021). "Galectin-3, an inflammatory mediator derived from microglia, participates in the pathophysiological process of various neurological diseases." (PMID 34900086, 2021).
brain disease (8 papers, 2019 to 2023). "High galectin-3 levels have been associated with neuroinflammation in a variety of brain diseases and proteome profiling provided first indications that the glycoprotein is also induced in human AMD." (PMID 36115971, 2022). "These conflicting functional roles of Galectin-3 after neuropathology could be due to the differential subcellular expression of Galectin-3 or due to the difference in the pathophysiology of brain disorders warranting further investigation." (PMID 31156388, 2019). "Galectin-3 (Gal3) is a lectin that has not been extensively explored in brain diseases." (PMID 31375685, 2019).
gastrointestinal tumors (8 papers, 2016 to 2024). "Regulatory DCs in Galectin-3:Toll-like receptor-4:Kynurenine-dependent manner promoted the expansion of colon-infiltrated T regulatory cells (Tregs) and suppressed Th1 and Th17 cell-driven colon inflammation." (PMID 31336879, 2019).
myopathy (8 papers, 2020 to 2025). A disease of the muscle in which the muscle fibers do not function properly. "The inactivation of VCP in skeletal muscle of adult mice leads to a necrotic myopathy, preceded by upregulation of LGALS3/Galectin-3, a typical marker of damaged lysosomes, and to the accumulation of autophagic proteins and of damaged lysosomes." (PMID 35273561, 2022).
benign neoplasm (6 papers, 2009 to 2023). A neoplasm which is characterized by the absence of morphologic features associated with malignancy (severe cytologic atypia, tumor cell necrosis, and high mitotic rate). "HFABP levels were significantly correlated to New York Heart Association classes and to established biomarkers of cardiac dysfunction and remodeling (amino-terminal pro-B-type natriuretic peptide [NT-proBNP], fibroblast growth factor 23, and galectin-3)." (PMID 37360894, 2023). "According to the results of this study, the ventricular diastolic function could be particularly affected by increased stiffness due to fibrosis of the heart, and galectin-3 could predict diastolic dysfunction." (PMID 34722704, 2021).
infectious disease (6 papers, 2017 to 2024). A disorder directly resulting from the presence and activity of a microbial, viral, or parasitic agent in humans. "Moreover, a higher plasma galectin-3 concentration was considered as an unfavorable prognostic factor for all-cause mortality, cardiovascular events, and infectious diseases of these patients." (PMID 34444962, 2021). "As a first example, extracellular Galectin-3 (LGALS3), detected in the blood of PDAC patients, has been associated with neutrophils recruitment and inflammation exacerbation in several infectious diseases." (PMID 37835519, 2023). "Galectin-3 is important for both the activation and recruitment of neutrophils in the immune response of infectious diseases." (PMID 35437453, 2022). "Galectin-3 is one of the galectin family members which are master regulators of immune homeostasis, especially in infectious diseases." (PMID 35437453, 2022). "The mainstream points of view on galectin-3 in infectious disease pathogenesis support it to be beneficial." (PMID 35437453, 2022). "Together, the current study supported the regulatory role of galectin-3 in the activation and recruitment of neutrophils in inflammatory diseases, especially infectious diseases." (PMID 35437453, 2022). "Our study was in agreement that galectin-3 knockout is detrimental to infectious disease recovery, leading to severe disease development and even corneal perforation." (PMID 35437453, 2022). "The role of galectin-3 in immune cell regulation remains to be unveiled which contributes most to the antipathogen immune response in infectious diseases, especially the regulation of neutrophils." (PMID 35437453, 2022). "The recruitment and activation effect of galectin-3 on neutrophils demonstrated that inhibition of galectin-3 could be the reason of the down-regulation of innate immune responses in inflammatory disorders, especially infectious diseases." (PMID 35437453, 2022).
connective tissue disease (5 papers, 2016 to 2024). "For fCEAA, there were many connective tissue disorders (due to the collagen protein family), as well as several proteins linked to miscarriage (COL5A1, IGFBP6, LGALS3); for fEAA, proteins were linked to immunological disorders, primarily due to the chemokine family and their receptors." (PMID 39401228, 2024). "Importantly, increased expression of Lgals3 and Icam1 was shown to be present in patients with IPAH and connective tissue disease." (PMID 31979420, 2020).
peripheral neuropathy (4 papers, 2017 to 2025). A disorder affecting the peripheral nervous system. "We also showed increased expression of p75 and galectin-3 in Schwann cells surrounding the neural axon in sciatic nerves isolated from mice with paclitaxel-induced peripheral neuropathy." (PMID 28729624, 2017). "However, caution is warranted when using galectin 3-LAMP1 staining in the context of the PNS, as recent data indicate an endogenous galectin 3 upregulation in dedifferentiated Schwann cells, which is relevant for peripheral neuropathies." (PMID 38672423, 2024). "Thus, therapies targeting SC-derived galectin-3 might represent a unique tactic to suppress taxane-related chemotherapy-induced peripheral neuropathy." (PMID 40940747, 2025).
vasculopathy (4 papers, 2015 to 2026). "Galectin-3 is involved in various pathological processes such as inflammation, proliferation, and fibrosis, but its role in the vasculopathy of PAH is poorly understood." (PMID 37367427, 2023). "Our study used a prevention design, as it is unlikely that the galectin-3 inhibitor (N-Lac) would be able to reverse the progression of vasculopathy in PAH." (PMID 37367427, 2023).
retinopathy (3 papers, 2018 to 2025). "The antiinflammatory effect of minocycline at the early stage of pericyte-depletion retinopathy was corroborated by the downregulation of CCL2, iNOS, TSPO, and LGALS3 in minocycline-treated APB5 retinas at P10." (PMID 40591415, 2025).
central nervous system diseases (2 papers, 2024). "Galectin-3 is a β-galactoside binding lectin that has been associated with inflammation in both systemic and central nervous system diseases." (PMID 39574161, 2024). "One protein that has been consistently linked to inflammation in both systemic and central nervous system diseases is the β-galactoside binding lectin; Galectin-3 (Gal-3, also known as Mac-2)." (PMID 39574161, 2024). "LGALS3 is observed to be upregulated in several central nervous system diseases associated with inflammation, including AD, hypoxia, and stroke." (PMID 39080267, 2024).
hematologic malignancies (2 papers, 2021 to 2025). "Previous studies have shown that galectin-3 (Gal-3) expression plays a role in many hematological malignancies." (PMID 40566589, 2025). "Galectin-3 is also shown to promote tumorigenesis in various solid tumors and hematologic malignancies and increased galectin-3 levels are reported in the bone marrow of aging mice." (PMID 34834485, 2021).
Intestinal fistulas (2 papers, 2020 to 2024). "Intestinal fistulas are mostly a complication of CD, but IBD patients with fistulas (14 patients) had similar serum (p = 0.323) and urine (p = 0.441) galectin-3 levels to patients without fistulas." (PMID 38731984, 2024).
blood cancers (1 paper, 2019). "In FVPTC samples, LGALS3, an IA gene, is strongly associated with genes associated with blood cancers (RUNX1, BCL2L1, CBFB, and TNFRSF1A), suggesting a strong immune association in LGALS3 activity." (PMID 31443155, 2019).
endocrine diseases (1 paper, 2021). "Although there have been no studies on the association between endocrine diseases and galectin-3 concentration in dogs, this study demonstrated significantly increased galectin-3 levels in dogs with endocrine diseases." (PMID 34722704, 2021). "This study revealed that significantly higher galectin-3 concentrations were found in dogs with endocrine diseases when dogs were grouped according to the disease category." (PMID 34722704, 2021). "Dogs with endocrine diseases (2.48 ± 2.56 ng/ml) had significantly elevated galectin-3 levels compared with healthy dogs (0.64 ± 0.15 ng/ml, p = 0.007)." (PMID 34722704, 2021). "Further research is required on the galectin-3 levels in dogs with endocrine diseases." (PMID 34722704, 2021). "However, a few studies have examined the circulating galectin-3 concentration in animals with endocrine diseases." (PMID 34722704, 2021).
LGALS3 also shares sentences with these, for which no sentence is quoted: acute myocardial infarction (39 papers); papillary carcinoma (12); Glucose intolerance (9); portal hypertension (9); tongue cancer (9); autoimmune hepatitis (6); end-stage renal disease (6); glomerulonephritis (6); acute myocarditis (5); carotid atherosclerosis (5); eosinophilia (5); head and neck cancer (5); abdominal aortic aneurysm (4); anaplastic large cell lymphoma (4); anaplastic thyroid carcinoma (4); Behçet’s disease (4); candidiasis (4); head and neck squamous cell carcinoma (4); hyperlipidemia (4); leishmaniasis (4); metastatic carcinoma (4); oral cancer (4); ST Elevation Myocardial Infarction (4); unstable angina (4); valvular heart disease (4); acute promyelocytic leukemia (3); angiosarcoma (3); arrhythmogenic right ventricular cardiomyopathy (3); bipolar disorder (3); complication (3).
A further 320 diseases each share a sentence with LGALS3 in 3 papers or fewer.